SNORD4B (small nucleolar RNA, C/D box 4B)
Synonyms: Z17B; RNU101B
Gene: Small nucleolar RNA gene on chromosome 17 (28,723,682 to 28,723,753, forward strand). Ensembl gene ENSG00000238597.
Gene Ontology:
Biological process: RNA processing
Cellular component: nucleolus
Homologues: Orthologues: chimpanzee SNORD4B (100% identical), macaque SNORD4B (99% identical), guinea pig SNORD4B (85% identical), pig SNORD4B (79% identical). Paralogues in human: SNORD4A (74% identical).